LRP4 (LDL receptor related protein 4)
Diseases named in the same sentence as LRP4 in open-access papers (continued):
Sharing a sentence is not in itself a finding about the gene and the disease.
Cenani-Lenz syndrome (16 papers, 2010 to 2025). "Surgical intervention was successful in addressing the defects at the skull base, and genetic testing revealed a rare mutation in the LRP4 gene, thus linking the clinical findings to Cenani-Lenz syndactyly syndrome." (PMID 40091967, 2025). "For the homologous LRP4 protein, we also noticed how a mutation that affects the aspartate at the same domain position (i.e. p.D137N of LRP4) is considered causal for Cenani–Lenz syndactyly syndrome." (PMID 38368933, 2024). "Most Lrp4 mutations in patients with Cenani-Lenz syndrome (CLS) are recessive and believed to alter its expression or function." (PMID 36765071, 2023). "LRP4 loss of function has been associated with developmental anomalies associated with Cenani–Lenz syndrome (CLS) disease, which includes limb malformation and renal agenesis." (PMID 32340285, 2020). "LRP4 is a strong suppressor of WNT signaling, and hence, loss-of-function mutations of LRP4 will lead to signal activation and syndactyly (Cenani–Lenz syndrome, OMIM 212780)." (PMID 31637260, 2019). "Mutations in LRP4 have been related to the Cenani–Lenz syndactyly syndrome and disruption of canonical WNT/beta-catenin signaling (OMIM 604270), which is not only important in bone formation but also in sexual development." (PMID 29670578, 2018). "In certain instances, Cenani–Lenz syndrome is caused by mutations that prevent Lrp4 from interacting with these negative regulators, leading to excessive Wnt and/or BMP signaling." (PMID 25407677, 2014). "Mutations in Lrp4 are responsible for Cenani–Lenz syndrome, characterized by bone abnormalities and fusions in hand, limb, and other bones." (PMID 25407677, 2014). "We have also shown that mutations in Lrp4 lead to the same or very similar developmental malformations as seen in human LRP4 deficient patients with Cenani-Lenz syndrome, further underscoring the importance of Lrp4 for human genetics and medicine." (PMID 20454682, 2010). "The Cenani-Lenz syndrome phenotype is related to various mutations of the LRP4 gene." (PMID 36195906, 2022). "Patients with Cenani-Lenz syndrome, an autosomal recessive disorder which results in syndactyly and oligodactyly and is caused by homozygous, mutation of LRP4, have seemingly normal NMJs, despite loss of LRP4 function." (PMID 33799485, 2021). "Another example is Cenani–Lenz syndrome (OMIM 212780) caused by LRP4 mutations." (PMID 31637260, 2019). "Moreover, although certain mutations in human Lrp4 cause Cenani-Lenz syndrome, characterized by bone malformations, other mutations in Lrp4, notably in one face of the third BP domain, impair binding to MuSK and cause congenital myasthenia." (PMID 29415504, 2018). "In addition, LRP4, a gene associated with Cenani-Lenz syndactyly syndrome and sclerosteosis, and ranked high (54th) for congenital muscular dystrophies, was implicated in a patient with a CMS disease." (PMID 25353622, 2014). "The identification of the LRP4 mutation in this patient establishes a possible genetic link between HCI and systemic syndromic conditions like Cenani-Lenz syndactyly syndrome." (PMID 40091967, 2025).
autoimmune disease (13 papers, 2015 to 2024). A disorder resulting from loss of function or tissue destruction of an organ or multiple organs, arising from humoral or cellular immune responses of the individual to their own tissue constituents. "Some studies that correlate sCP and autoantibodies in autoimmune diseases showed that high levels of sCP have been associated with positive autoantibodies (Ab-anti-dsDNA, anti-SSA, anti-Ro60, AchR-Ab, Musk-Ab, LRP4-Ab, levels of MPO and PR3...)." (PMID 38792945, 2024). "MG is an autoimmune disease that affects proteins in the neuromuscular junction (AChR, MuSK, and Low-Density Lipoprotein Receptor Related Protein-4—LRP4)." (PMID 39335511, 2024). "MG is an autoimmune disease of the neuromuscular junction characterised by the presence of skeletal muscle weakness caused by antibodies directed against AChR, muscle-specific kinase (MUSK), or low-density lipoprotein receptor-related protein 4 (LRP4)." (PMID 36829670, 2023). "MG is an autoimmune disease caused by antibodies directed against key molecules at the NMJ, such as the nicotinic acetylcholine receptor (AChR), muscle-specific kinase (MuSK), and low-density lipoprotein receptor-related protein 4 (Lrp4), or agrin in the postsynaptic membrane." (PMID 34140924, 2021). "MG is a B-cell mediated organ-specific autoimmune disease with antibodies against the acetylcholine receptor, muscle-specific kinase (MUSK), lipoprotein-related protein 4 (LRP4), or agrin in the post-synaptic membrane at the neuromuscular junction." (PMID 32982946, 2020). "Case reports of concomitant autoimmune disease in the LRP4-MG subgroup are still lacking." (PMID 25915571, 2015).
congenital myasthenic syndrome (13 papers, 2014 to 2025). Congenital myasthenic syndrome (CMS) is a group of genetic disorders of impaired neuromuscular transmission at the motor endplate characterized by fatigable muscle weakness. "In particular, we validated a novel exon in Lrp4, a gene mutated in congenital myasthenia, in mice and humans." (PMID 39945189, 2025). "Finally, we were able to detect and validate a novel exon in Lrp4, ortholog of a gene implicated in congenital myasthenic syndrome in human." (PMID 39945189, 2025). "Components of the LRP4/MuSK/Dok-7 complex are the targets of mutations responsible for subsets of congenital myasthenic syndromes (CMS), which are characterized by fatigable muscle weakness." (PMID 29462491, 2018). "Mutations in Lrp4 that reduce Agrin–Lrp4–MuSK signaling, without perturbing Wnt signaling, cause a neuromuscular disease, termed congenital myasthenia." (PMID 25407677, 2014).
sclerosteosis (12 papers, 2014 to 2024). "This variant is causal for sclerosteosis when present as heterozygous compound mutation together with another pathogenic variant in LRP4 (p.R1170Q)." (PMID 38244079, 2024). "Thanks to in vitro functional studies, it has been proven that all these mutations cause a significant decrease in the inhibition of the canonical Wnt pathway by LRP4, this effect being more severe in mutations associated with sclerosteosis-2." (PMID 35052478, 2022). "Instead, impaired binding between sclerostin and LRP4 has been verified in the mutations causing sclerosteosis, which would explain the severity of the effect." (PMID 35052478, 2022). "In conclusion, we report the identification of two compound heterozygous variants, p.Arg1170Gln and p.Arg632His, in LRP4 in a patient with a sclerosteosis phenotype." (PMID 35052419, 2021). "In conclusion, this study is the first to demonstrate that a pathogenic variant in the first β-propeller domain of LRP4 can contribute to the development of sclerosteosis, which broadens the mutational spectrum of the disorder." (PMID 35052419, 2021). "In the current study, we performed a mutation analysis of the SOST and LRP4 genes in a sclerosteosis patient, identifying compound heterozygous variants in the first and third β-propeller domain of LRP4." (PMID 35052419, 2021). "Sclerosteosis is a high bone mass disorder, caused by pathogenic variants in the genes encoding sclerostin or LRP4." (PMID 35052419, 2021). "Our study shows the identification and functional investigation of two compound heterozygous variants in LRP4 in a Spanish sclerosteosis patient." (PMID 35052419, 2021). "This was evidenced by the identification of disease-causing variants in LRP4 or SOST in sclerosteosis patients, a severe sclerosing bone disorder specifically characterized by progressive bone overgrowth." (PMID 35052419, 2021). "So far, we and others were able to identify three sclerosteosis-causing variants in LRP4 (p.Trp1186Ser, p.Arg1170Trp, p.Arg1170Gln)." (PMID 35052419, 2021). "The characterization of bone response in Ta mice can be adapted to other mutant mice presenting skeletal abnormalities and described in the literature like the Lrp4 mutated sclerosteosis mouse model or the mutant FKBP51V55L for Paget's disease." (PMID 29682553, 2018). "In addition to these models, LRP4-KI mouse models with the p.R1170W or p.R1170Q mutations, which cause sclerosteosis in humans, recapitulate the human HBM phenotype associated with this mutation without the presence of syndactyly." (PMID 35052478, 2022). "Interestingly, the other heterozygous variant (p.Arg632His) has not been reported before, and is located outside the region in LRP4 that is usually mutationally affected in sclerosteosis patients." (PMID 35052419, 2021). "Until now, the majority of mutations identified in the LRP4 gene causing bone diseases including CLS and sclerosteosis-2 are the result of the role of LRP4 signaling in autopod formation and kidney development." (PMID 37640745, 2023). "The majority of mutations identified in LRP4 gene causes bone diseases including CLS and sclerosteosis-2 and rare cases of CMS with mutations in LRP4 gene has been described so far." (PMID 37640745, 2023). "Sclerosteosis 2 has been mapped to the LRP4 gene where there is direct interaction between sclerostin and LRP4, and LRP4 facilitates sclerostin mediated WNT inhibition; which is implicated in LRP4 mutants." (PMID 35549993, 2022). "Ten years after the identification of SOST as the disease-causing gene, pathogenic variants in LRP4, which encodes the low-density lipoprotein receptor-related protein 4 (LRP4), were identified in SOST-negative sclerosteosis patients." (PMID 35052419, 2021). "As the patient was thought to suffer from sclerosteosis, SOST and LRP4 were analyzed for putative variants." (PMID 35052419, 2021).
sclerosteosis (continued). "CLS-causing mutations decrease the levels of LRP4 available in the membrane, while this is not observed for the sclerosteosis-causing mutations." (PMID 35052478, 2022). "Recently, the importance of the third β-propeller domain has been emphasized by the successful generation of two novel mouse models, the Lrp4 Arg1170Gln knock-in mouse and the Lrp4 Arg1170Trp knock-in mouse, both recapitulating the sclerosteosis phenotype observed in human patients." (PMID 35052419, 2021). "Besides sclerosteosis, other LRP4-related disorders have been described, in which the disease-causing variants are located outside this specific region of the LRP4 protein." (PMID 35052419, 2021). "The phenotypic heterogeneity of these diseases ranging from congenital malformations affecting the limbs for CLS and sclerosteosis 2 to fatigability and muscle weakness for CMS suggest that LRP4 may have several specific functions acting on different organs in a timely manner." (PMID 37640745, 2023). "In addition, two mutations in low-density lipoprotein receptor-related protein 4 (LRP4) have been found in sclerosteosis patients, independent of the sclerostin genotype, demonstrating that LRP4 interacts with sclerostin or mediates its function." (PMID 35563144, 2022).
thymoma (10 papers, 2016 to 2025). A neoplasm arising from the epithelial cells of the thymus. "The significance of the association between LRP4-MG and neoplasms, including thymoma and lung cancer remains to be investigated." (PMID 29518096, 2018). "Among the 10 reported cases with both AChR/LRP4 antibodies and thymic abnormalities, 2 cases (20%) had thymoma, and 6 cases (60%) had thymic hyperplasia." (PMID 40356916, 2025). "Two patients were positive for anti-LRP4 Abs, one with late onset generalized MG with small cell lung cancer and the other with thymoma." (PMID 37759888, 2023). "Clinically, anti-AChR/LRP4 antibodies double-seropositive MG is rare, often onset after middle age, more common in females, frequently involving bulbar muscles, severe symptoms, poor prognosis, and unrelated to thymoma." (PMID 40356916, 2025). "Furthermore, AChR+Titin-MG shows a shorter conversion time from ocular to generalized MG, a higher incidence of thymoma, and has a more severe presentation than AChR+LRP4-MG." (PMID 35614931, 2022). "One patient had thymoma, which is an unusual finding in LRP4-MG, just as in MuSK-MG." (PMID 29518096, 2018). "Patients with LRP4-MG had mild symptoms at disease onset (81% had MGFA grade I or II), with some thymic changes identified (32% hyperplasia, none with thymoma)." (PMID 37759888, 2023).
Alzheimer disease (9 papers, 2012 to 2024). A progressive, neurodegenerative disease characterized by loss of function and death of nerve cells in several areas of the brain leading to loss of cognitive function such as memory and language. "This body of evidence indicates the potential for LRP4 as a therapeutic target, and the need for further study of the roles of LRP4 in Alzheimer’s disease, and the CNS." (PMID 33799485, 2021). "Connecting to Alzheimer’s disease, dementia, and amyloidosis hubs include prominent AD-associated proteins such as the low-density lipoprotein receptor-related proteins LRP1, LRP1B, LRP4, and LRP6." (PMID 33946285, 2021). "More recently, it has been demonstrated that LRP4 is reduced in the brain of patients with Alzheimer disease (AD), paralleling the reduced levels in an AD mouse model that are associated with exacerbation of cognitive impairment and increases in the amount of amyloid aggregates." (PMID 34849350, 2021). "Finally, emerging roles in CNS function have highlighted a potential role for LRP4 in Alzheimer’s disease (AD)." (PMID 33799485, 2021). "To date, Lrp4 is known to be involved in a myriad of processes, such as limb anomalies, craniofacial organogenesis, kidney malformations, adult hippocampal neurogenesis, ALS, and Aβ clearance in Alzheimer’s disease." (PMID 34063992, 2021).
myasthenia (8 papers, 2013 to 2026). "Thus interference by IgG4 antibodies of the LRP4-MuSK interaction will be one pathogenic mechanism of MuSK antibodies, but IgG1-3 MuSK antibodies will also contribute to the reduced AChR density and neuromuscular dysfunction in myasthenia patients with MuSK antibodies." (PMID 24244707, 2013). "Myasthenia-specific antibodies (acetylcholine receptor (AChR), muscle-specific kinase (MuSK), low-density lipoprotein receptor (LRP4)) may be positive, indicating the presence of concurrent myasthenia, especially when ocular or bulbar symptoms are predominant." (PMID 38927526, 2024). "Here, we describe two anti-LRP4 antibody-seropositive ALS patients with myasthenia." (PMID 27863479, 2016). "Consequently, differences between patients with LRP4 myasthenia described so far and our patient with both CMS and CLS could be due to the consequences of direct binding defects of agrin to the mutated β1 propeller domain of LRP4." (PMID 37640745, 2023). "We report two anti-LRP4 antibody-seropositive ALS patients with myasthenia who were not typical of ALS patients, and showed partial responses to immunotherapies." (PMID 27863479, 2016).
epilepsy (5 papers, 2014 to 2025). A brain disorder characterized by episodes of abnormally increased neuronal discharge resulting in transient episodes of sensory or motor neurological dysfunction, or psychic dysfunction. "Collectively, these data suggest that Lrp4 in pyramidal neurons is dispensable for seizure susceptibility and SE-induced epilepsy." (PMID 38783336, 2024). "The exact mechanisms underlying Lrp4 regulation of adenosine during the development of epilepsy await to be determined in future study." (PMID 38783336, 2024). "Accordingly, it will be interesting to explore whether Lrp4-deficient mice are predisposed to additional autism-like phenotypes such as altered social behavior, hyperactivity, and epilepsy." (PMID 25407677, 2014). "Together, these observations suggest that agrin promotes SE-induced epilepsy in an Lrp4-dependent manner." (PMID 38783336, 2024). "Our study identifies a vital role of agrin-Lrp4 signaling in regulating the development of SE-induced epilepsy." (PMID 38783336, 2024). "A parsimonious interpretation is that SE induces over-release of agrin in the hippocampus, which binds to astrocytic Lrp4 and aggregates the development of SE-induce epilepsy." (PMID 38783336, 2024). "We found that agrin infusion into ventricle promoted the development of SE-induced epilepsy which is dependent of Lrp4 in the astrocytes." (PMID 38783336, 2024). "To examine the role of Lrp4 in the development of epilepsy, we generated brain-specific Lrp4 mutant mice by crossing hGFAP::Cre mice with Lrp4-flanked (Lrp4f/f) mice." (PMID 38783336, 2024). "Altogether, these data suggest that deletion of astrocytic Lrp4 in the hippocampus exhibits suppressive effects on SE-induced epilepsy." (PMID 38783336, 2024). "We found that deletion of Lrp4 in the astrocytes increased extracellular adenosine level during the development of epilepsy, providing a novel molecular mechanism for adenosine regulation." (PMID 38783336, 2024). "Please note that in the present study we only studied the role of astrocytic Lrp4 in the hippocampus on status epilepticus-induced epilepsy at adult stage." (PMID 38783336, 2024). "In contrast, we report that specific knockdown of Lrp4 in the astrocytes of the hippocampus duplicated the phenotypes of brain-wide Lrp4 mutant mice (hGFAP-Lrp4−/−), demonstrating that astrocytic Lrp4 in the hippocampus is critical in regulation of the development of SE-induced epilepsy." (PMID 38783336, 2024). "Nevertheless, whether the effects of Lrp4 signaling on epilepsy is generally applied in distinct epilepsy models, such as pilocarpine and pentylenetetrazol-induced seizure models, is not clear, which is worth being examined in future study." (PMID 38783336, 2024). "In light that epilepsy could occur at any age and the incidence rate is higher in children than in adult, it would be interesting to examine whether the effects of Lrp4 in hippocampal astrocytes on epilepsy varies at different age in the future study." (PMID 38783336, 2024). "On the other hand, it is still not clear whether Lrp4 locates in the GABAergic inhibitory neurons in the brain and plays a role in the development of epilepsy, which warrants further investigation." (PMID 38783336, 2024). "How is adenosine level regulated by Lrp4 during epilepsy is not understood yet." (PMID 38783336, 2024). "In the present study, we present in vivo evidence to demonstrate that astrocytic Lrp4 in the hippocampus regulates the development of SE-induced TLE through adenosine signaling, which sheds light on the development of new therapeutic interventions for epilepsy." (PMID 38783336, 2024).
sclerosteosis 2 (5 papers, 2015 to 2023). Any sclerosteosis in which the cause of the disease is a mutation in the LRP4 gene. "Sclerosteosis type 2 causing mutations in LRP4 are located in the third β-propeller domain and result in decreased binding of sclerostin." (PMID 32328030, 2020). "Mutations in LRP4 can cause sclerosteosis type 2, Cenani–Lenz syndrome (CLS), isolated syndactyly, and congenital myasthenia gravis depending on type and location of the mutations." (PMID 32328030, 2020).
hepatocellular carcinoma (4 papers, 2018 to 2022). A malignant tumor that arises from hepatocytes. "Finally, a recent report from a completely unrelated field of cell biology, the etiology of hepatocellular carcinoma, presents an intriguing possibility for a unified mechanism for synaptogenesis involving integrin, agrin and Lrp4-MuSK signaling." (PMID 31744142, 2019). "Besides, it has also been observed that agrin is overexpressed and secreted in tumor cells such as hepatocellular carcinoma (HCC), and is responsible for enhancing tumor cell proliferation and migration via the Lrp4/MuSK signaling." (PMID 35174224, 2021).